CRP (C-reactive protein)
Diseases named in the same sentence as CRP in open-access papers (continued):
Sharing a sentence is not in itself a finding about the gene and the disease.
infection (continued). "As an important biomarker in clinical diagnosis, CRP detection is also used in clinical medicine to detect and monitor various diseases, including infections, autoimmune disorders, and certain tumors." (PMID 38067596, 2023). "In this study, leukocyte count and C-reactive protein on the first postoperative day were selected as indicators of infection, and hemoglobin and albumin on the first postoperative day were used as biochemical indicators for observation." (PMID 37940888, 2023). "According to this algorithm, if CRP is over 82 mg/L, the probability of infection is very high (above 90%) and an infection source must be sought." (PMID 37016028, 2023). "A Kruskal–Wallis H test was performed to compare the levels of PCT and CRP among various infection site subgroups." (PMID 37821527, 2023). "A reexamination of the infection indicators found significantly abnormal results: CRP 97.1–107.7 mg/L, PCT 11.1–13.41 ng/mL; fecal occult blood (+)." (PMID 38132208, 2023). "Complementarily, C-reactive protein (CRP) is considered an important biomarker of infection and inflammation for a number of diseases." (PMID 37259395, 2023). "CRP has served as a useful marker of infection and tissue inflammation for several decades, and has been shown to be regulated by the pro-inflammatory cytokines TNF-α and IL-6 in an in vitro study." (PMID 36936907, 2023). "CRP is the major acute phase protein that shows a dynamic and marked increase in serum concentration during infection or as a result of tissue damage." (PMID 36670722, 2023). "First, CRP was discovered as a general biomarker for inflammation and infection and established in clinical practice." (PMID 37626775, 2023). "Her glucocorticoid was reduced due to severe infection and then she had high fever, CRP increased rapidly, hemoglobin decreased, and her pulmonary symptoms were significantly aggravated." (PMID 36961149, 2023). "Using those, PSP (AUC 0.80, 95%CI [0.75–0.85]) and PCT (AUC 0.79, 95%CI [0.74–0.84]) performed better that CRP (in stratifying patient according to infection severity: AUC was lowest for CRP (AUC 0.56, 95%CI [0.50–0.63])." (PMID 37707744, 2023). "C-reactive protein is a positive acute phase reactant that increases in response to infection, trauma, tissue damage, cardiovascular disease, and other inflammatory events." (PMID 36788868, 2023). "The examination of PCT and CRP levels across different infection sites revealed intriguing patterns." (PMID 37821527, 2023). "IL-6 and CRP were both increased in infants diagnosed with postnatal infection, with peak levels observed on days 2 and 3, respectively." (PMID 37606448, 2023). "In the presence of infection, CRP plays dual roles by exerting both proinflammatory and anti-inflammatory effects." (PMID 38109177, 2023). "A total of 54/138 (39%) children received antibiotics, of whom 37 showed increased C-reactive protein amounts suggestive of bacterial over-infection, and 28 of whose X-rays showed thickening suggestive of bacterial infection." (PMID 36992426, 2023). "C‐reactive protein (CRP) is a sensitive biomarker of inflammation and is routinely monitored in acute and chronic inflammatory conditions, including infections, inflammatory bowel diseases, autoimmune disorders, and cardiovascular diseases." (PMID 37493001, 2023). "Thirdly, various factors can raise CRP levels, including trauma, infection, inflammation, and tumor stimulation." (PMID 38053048, 2023). "Infection-related biomarkers such as IL-6 and CRP are widely used to predict disease progression and prognosis." (PMID 37894092, 2023). "High levels of tumor necrosis factor (TNF), C-reactive protein (CRP), and interleukin 6 (IL-6) point to the involvement of infection and inflammation in the etiology of GDM." (PMID 36993820, 2023). "The reduced count of Escherichia coli coincides with the reduced inflammatory markers (ESR of 77 (mm/hr) and CRP of 42 (mg/L)), suggesting the infection was subsiding." (PMID 37303456, 2023).
infection (continued). "In healthy individuals, CRP levels are very low (<1 μg/mL), but they rapidly increase during infections, tissue damage, or inflammation." (PMID 38005386, 2023). "CRP is an acute-phase protein synthesized by the liver in response to inflammation and is commonly utilized as an indicator of systemic inflammation and infection." (PMID 37685276, 2023). "CRP is known to be negatively correlated with the glomerular filtration rate; nevertheless, it can properly predict infection in patients with impaired renal function." (PMID 37238265, 2023). "Both CRP and IL-6 are established biomarkers for postnatal infection, but their relative utility and specificity are debated." (PMID 37606448, 2023). "In our study, we excluded patients diagnosed clinically with infection and started on antibiotics, and those in whom the C reactive protein (CRP) was greater than 20 mg/L." (PMID 36483266, 2023). "Plasma C-reactive protein (CRP) is a marker of inflammation and infection that has been associated with preterm delivery when concentrations are high." (PMID 38130330, 2023). "The hepatocytes produce CRP, an acute-phase protein, in response to inflammation, infection, and neoplasm." (PMID 37189111, 2023). "The CRP increase is a positive acute phase reactant, and it responds to infection, trauma, tissue damage, cardiovascular disease, and other inflammatory events." (PMID 36788868, 2023). "In B. rossi, CRP elevates significantly during infection in concert with disease progression and decreases with resolution but does not predict outcome." (PMID 38133320, 2023). "In the management of cancer, a high ESR is associated with an unfavorable prognosis in malignancies due to an increase in serum proteins, such as CRP, in response to inflammation, infection, and malignancy." (PMID 37987280, 2023). "The previous study, specifying the cutoff values of both procalcitonin and CRP for early detection of infection in hemodialysis patients, was able to lower the cutoff point of CRP to 19.15 mg/L, through the combined use of procalcitonin and CRP5." (PMID 37016028, 2023). "The aim of the present study is to investigate and analyze PCT in odontogenic purulent infections of the head and neck in the female population and to compare it with already proven markers of inflammation such as CRP, WBC, and Neu." (PMID 38050495, 2023). "In the study, we assessed that CRP had a high correlation with the severity of infection, based on a statistically significant correlation between CRP level and the size of swelling in patients treated in our hospital (p < 0.05)." (PMID 36670722, 2023). "Although infections that raised plasma CRP to a level of 100 mg/L or higher were frequent and occurred among 40% of the patients, only 5% died within 30 days from an infection episode." (PMID 37314998, 2023). "The relatively short half-life is an advantage of both prealbumin and CRP, which makes them considered sensitive indicators of infection." (PMID 36670722, 2023). "Conventional CRP assays are used when evaluating an infection, tissue injury, or inflammatory disorder." (PMID 38001962, 2023). "C-reactive protein (CRP) is a positive acute-phase protein of the pentraxin family that increases in serum with systemic inflammation, infection, and cancer." (PMID 37888572, 2023). "As a result, mFi-5 score, elevated CRP, abnormal WBC and signs of severe local tissue infection were included in the proposed perianal sepsis risk score for perianal abscesses." (PMID 37629259, 2023). "When the body is exposed to infection, injury, or inflammation, the production of CRP increases rapidly." (PMID 38067596, 2023). "CRP is a protein produced by the liver that increases when inflammation or infection occurs in the body." (PMID 37763758, 2023). "When CRP values are below 20 mg/L and when the clinical assessment supports ruling out a severe infection, it is strongly suggested to avoid prescribing antibiotics." (PMID 37900677, 2023).
infection (continued). "After infection, C-reactive protein can enhance the phagocytosis of phagocytic cells by complement activation and play a critical role in innate host defense." (PMID 36873397, 2023). "CRP is a sensitive marker that is elevated as an acute-phase response in inflammation, tissue damage, and infection." (PMID 37260778, 2023). "C-reactive protein (CRP) is γ-globulin produced by the liver and classified as an acute phase reactant, which means that it rises in response to general inflammation, infection, or tissue injury following IL-6 secretion by macrophages." (PMID 37542317, 2023). "The significant survival difference between patients with normal and elevated CRP (≥ 5 mg/L) persisted after exclusion of patients with clinical infection (93 vs. 20 months, p = 0.043)." (PMID 36441359, 2023). "Upon tissue damage or infection, while CRP levels are rising, pCRP → mCRP conversion is rapid with overall CRP function exhibiting mCRP’s proinflammatory characteristics." (PMID 37781355, 2023). "Acute-phase response to infection includes an increase in C-reactive protein (CRP) and α1-acid glycoprotein (AGP) and a decrease in serum concentrations of retinol and RBP." (PMID 37974246, 2023). "A secondary increase in CRP in the postoperative course is suggestive of infection as is a tenfold elevation of the normal value in the first postoperative week." (PMID 37243789, 2023). "The C-reactive protein level is a common indicator of inflammation and infection and is often used to assess their severity." (PMID 36691024, 2023). "We found that C-reactive protein and procalcitonin in the extrapancreatic infection group were significantly higher than those in the non-infection group." (PMID 36755607, 2023). "At the early stages of infection, CRP has unsatisfactory low sensitivity; therefore, periodic measurements of CRP at 24-48 hours alleviate its sensitivity and negative predictive value and are thus beneficial for supervising treatment." (PMID 37868444, 2023). "Of note, these performances were overestimated given that CRP and clinical variables were part of the parameters used by the adjudicators to assign the infection status of patients." (PMID 37371798, 2023). "The C-reactive protein (CRP) test is the most straightforward and convenient method for quantitatively assessing inflammation and is commonly used to evaluate the intensity of infection and inflammation in various infectious diseases." (PMID 38137581, 2023). "CRP is a protein composed of five subunits synthesized by the liver which reacts to the acute phase of an inflammatory/infection process, mainly due to the action of IL-6 on the gene that controls CRP transcription." (PMID 37111388, 2023). "Infection with norovirus also increases CRP, AGP, and HAMP, and promotes changes in levels of micronutrients iron and vitamin A." (PMID 36675141, 2023). "What is more, ADAMTS-13 levels were positively correlated with PLT count in the acute phase of infection (r = 0.507, p = 0.045) and negatively correlated with CRP (r = −0.787, p < 0.001)." (PMID 37886991, 2023). "It is more recognized that continuous normal values of biomarkers like CRP and procalcitonin over the first 48 hours of age can help to eliminate infection and shorten the course of antibiotics." (PMID 36698176, 2023). "CRP is known to be largely produced by hepatocytes and can increase by a factor of 1,000 at infection sites." (PMID 37860004, 2023). "The probability of major infection was < 0.1 when postoperative day‐3 CRP was ≤ 100 mg.l‐1 and approximately 0.9 for ≥ 500 mg.l‐1." (PMID 37531295, 2023). "Data from other patients demonstrated that hBD2 followed the pattern of CRP from the time point of peaking and after the treatment of the infection." (PMID 37296737, 2023). "The survival difference between patients with normal (< 5 mg/L) and elevated CRP levels persisted after exclusion of patients with clinical infection." (PMID 36441359, 2023).
infection (continued). "We feel that the overlap between both clinical and chemical presentations of bacterial infection and CRS is what rendered WBC count and CRP inconsequential for a differential diagnosis specific for infection." (PMID 36752185, 2023). "As an acute response protein and an inflammatory marker, C-reactive protein (CRP) can respond to infection, inflammation, and tissue damage, and its plasma concentration rises rapidly, even up to 10,000 times." (PMID 37025371, 2023). "Lower serum albumin and higher hs-CRP levels in group 1 patients were evidence of ongoing subclinical inflammation and/or infection status." (PMID 38092856, 2023). "CRP which is an acute-phase reactant that is synthesized by the liver in the setting of infection or tissue injury plays an important role in producing proinflammatory cytokines." (PMID 36701309, 2023). "Further, it was recently demonstrated that during COVID19, initial CRP levels determine distinct inflammatory profiles, which have distinct clinical courses and outcome of infection." (PMID 38066442, 2023). "The AUC of P-SEP calculated from the ROC curves in the infection group was significantly greater than that of procalcitonin, CRP, and IL-68." (PMID 38057335, 2023). "Among nine patients with death as an outcome, qSOFA was elevated in all the patients; AC was present in 11%; evidence of infection was present in 44%; disease flare and elevated CRP was found in all the patients." (PMID 37050995, 2023). "There are however, data in the literature of the combined use of CRP with procalcitonin, another infection marker, in dialysis patients, to differentiate between infectious and noninfectious inflammations." (PMID 37016028, 2023). "The table below summarizes several studies performed in primary care and in emergency department settings related to the effectiveness of CRP POCT in children to safely reduce antibiotic prescribing rates or rule in or out serious infection." (PMID 37900677, 2023). "Overall, there was not a statistically significant interaction between postnatal age and infection status for IL-6 (p = 0.08), but a significant interaction was present for CRP (p < 0.001)." (PMID 37606448, 2023). "WBC count and CRP level are indicators of inflammation; patients with higher inflammatory markers have a higher possibility of infection progression." (PMID 37685275, 2023). "Univariate analysis revealed that the P-values of CRP, modular component exchange, duration of symptoms, and different types of infection were <0.1 for treatment failure and were entered into the Cox proportional hazards regression model." (PMID 36117805, 2022). "Patients with definitive infection group demonstrated significantly higher median serum CRP levels (24.3 mg/l), when compared to probable, possible infection groups and PJI unlikely group (8 mg/l, 8.3 mg/l, 3.6 mg/l, respectively, p < 0.05)." (PMID 33515325, 2022). "In a study among Slovenian children, infection with p1 type 2 strains resulted in an elevated C-reactive protein level and a higher rate of hospital admissions in comparison with p1 type 1 infections." (PMID 35722324, 2022). "When CRP levels remain unremarkable or low at follow-up measurements, a relevant severe infection is very unlikely." (PMID 36294849, 2022). "CRP is an acute-phase protein, which is a plasma protein produced by the liver that rises sharply during infection or tissue damage." (PMID 35401167, 2022). "During infection, pro-inflammatory markers—C-reactive protein (CRP), interleukin-6 (IL-6) as well as interferon-gamma-inducible protein-10 (IP-10)—respond acutely." (PMID 35682203, 2022). "Existing host-derived biomarkers of infection include C-Reactive Protein (CRP), procalcitonin, hematologic markers, and more recently, the proposal to monitor lipocalin release from N-formyl-methionyl-leucyl-phenylalanine stimulated whole blood neutrophils." (PMID 36292097, 2022).
infection (continued). "Beside CRP, we found correlations between kynurenine and peak IL-6 values in the acute infection phase." (PMID 36211365, 2022). "C-reactive protein (CRP) is a member of the highly conserved pentraxin superfamily of proteins and is often used in clinical practice as a marker of infection and inflammation." (PMID 36177015, 2022). "Growing studies have shown that CRP plays important roles in inflammatory processes and host responses to infection, including the complement pathway, apoptosis, phagocytosis, nitric oxide release, and the production of cytokines." (PMID 36275680, 2022). "CRP is the classical acute phase reactant, and the circulating concentration rises rapidly in a cytokine-mediated response to tissue injury, infection, and inflammation." (PMID 35888682, 2022). "C-reactive protein (CRP) is an established biomarker of infection since it was first described in 1930 by Tillet and Francis and can be used as a reliable and fast indicator of the extent of inflammation in the human body." (PMID 35407564, 2022). "CRP and PCT are commonly used and less expensive clinical detection methods directly linked to infection severity and is found to be increased by infections." (PMID 36189371, 2022). "The proportion with troponin I and CRP values above the upper-limit threshold was comparable between pre- and post-infection (5.9% vs 5.9%, and 5.6% vs 8.7%, respectively)." (PMID 35751748, 2022). "In the present study, a downward trend in log CRP was observed after excluding the 2 cases in which infection was strongly suspected." (PMID 35949598, 2022). "CRP, C-reactive protein, is often measured as a broad-scale marker of inflammation in infection and auto-immune/rheumatologic conditions." (PMID 35700185, 2022). "In our study, the finding of elevated values of heart rate, total NEWS score, and CRP supported the infection diagnosis." (PMID 35406374, 2022). "CRP is a positive type II acute-phase protein expressed in the liver in response to infection, inflammation, or cancer." (PMID 36213409, 2022). "In comparison to odontogenic infections, CRP is a better infection measure than WBC because its level rises more rapidly." (PMID 36676644, 2022). "CRP on postoperative day 1, day 3 and day 6 after cesarean section stratified by surgical site infection and emergency/elective CSa." (PMID 36083881, 2022). "Given its stability and constant half-life, CRP’s concentration can be increased rapidly within the first 4–6 h after the occurrence of the infection." (PMID 35585489, 2022). "These include persistent fever for more than 72 hours, community-onset of infection, delay in treatment, and high C-reactive protein (CRP) levels for more than two weeks after the beginning of antibiotics." (PMID 35494918, 2022). "CRP is often used as a marker of inflammation and is reported to be useful for detecting infections in the head and neck region." (PMID 36503406, 2022). "We focused upon groups of patients with a similar range of CRP concentration (iso-CRP groups) and provided the probability of the infection being bacterial in origin in each group." (PMID 36477474, 2022). "The disappearance of inflammatory manifestations and regression of infection indicators (such as interleukin-6 (IL-6), C-reactive protein, white blood cell count) to the normal range were regarded as radical debridement." (PMID 36299571, 2022). "Twenty-two patients (42.3%) from the infection group had a normal (< 10 mg/l) serum CRP level prior to revision surgery." (PMID 33515325, 2022). "Previous studies have demonstrated the possibility of using CRP as a marker for infection-related complications after gastrointestinal operations." (PMID 35151339, 2022). "During SARS-CoV-2 studies in non-human primates, we recently observed that haptoglobin levels, in comparison with CRP, had the same early increase 2 days after infection, but remained more consistently elevated for at least 10 days post-infection." (PMID 35327501, 2022).